PCDHB14 (protocadherin beta 14)
Description:
Potential calcium-dependent cell-adhesion protein. May be involved in the establishment and maintenance of specific neuronal connections in the brain.
Synonyms: PCDH-BETA14
Tractability: Antibody: UniProt places it where antibodies can reach, with medium confidence; UniProt predicts a signal peptide or a membrane-spanning region; its Gene Ontology location is reachable by antibodies, with medium confidence. PROTAC: ubiquitination databases record sites on it.
Gene: Protein-coding gene on chromosome 5 (141,223,343 to 141,227,759, forward strand). Ensembl gene ENSG00000120327.
Subcellular location: Cell membrane
Subcellular location (Human Protein Atlas): Vesicles
Gene Ontology:
Molecular function: protein binding; cell adhesion molecule binding; calcium ion binding
Biological process: calcium-dependent cell-cell adhesion; cell adhesion; chemical synaptic transmission; synapse assembly; homophilic cell-cell adhesion; nervous system development
Cellular component: membrane; plasma membrane; synapse
Genetic constraint (gnomAD): Loss-of-function variants: 2 observed, 1.26 expected, observed/expected ratio (o/e) 1.59, 90% interval 0.47 to 1.93. That is too few expected variants to judge how well the gene tolerates losing a copy. Missense variants: 1,129 observed, 1,018.4 expected, observed/expected ratio (o/e) 1.11, 90% interval 1.05 to 1.16. Synonymous variants: 511 observed, 440.95 expected, observed/expected ratio (o/e) 1.16, 90% interval 1.08 to 1.25.
Homologues: Orthologues: chimpanzee PCDHB14 (98% identical), dog PCDHB14 (85% identical), mouse Pcdhb20 (79% identical). Paralogues in human: PCDHB2 (78% identical), PCDHB11 (77% identical), PCDHB3 (76% identical), PCDHB12 (76% identical), PCDHB16 (75% identical), PCDHB7 (75% identical), PCDHB4 (75% identical), PCDHB15 (75% identical), PCDHB10 (74% identical), PCDHB9 (74% identical), PCDHB5 (74% identical), PCDHB6 (74% identical), and 49 more.
Diseases named in the same sentence as PCDHB14 in open-access papers:
PCDHB14 is named in the same sentence as 6 diseases in open-access papers, as found by Europe PMC text mining. Sharing a sentence is not in itself a finding about the gene and the disease. The quoted sentences say what the papers report.
diabetes (1 paper, 2022). "There were 8 differentially methylated genes (CDH2/PCDHB10/PCDHB11/PCDHB14/PCDHB16/PCDHB3/PCDHB6/PCDHB9) in the LAA subgroup and 1 (CDH2) in the SVD subgroup after adjusting for smoking, drinking, history of hypertension and diabetes, and blood lipid levels (p < 0.05)." (PMID 35480311, 2022).
hepatocellular carcinoma (1 paper, 2024). A malignant tumor that arises from hepatocytes. "The 5-Aza decreased the methylation level of protocadherin beta 14 (PCDHB14), which induces ferroptosis in hepatocellular carcinoma cells." (PMID 38392340, 2024).
lung adenocarcinoma (1 paper, 2014). A carcinoma that arises from the lung and is characterized by the presence of malignant glandular epithelial cells. "Interestingly, although somatic mutation is rare in EGFR/KRAS/ALK-negative lung adenocarcinoma of never-smokers, the PCDHB14 (cell adhesion) Y670S mutation and YTHDF1 (RNA binding) I492V mutations were each found in two cases (12.5%)." (PMID 24576404, 2014).
tumor (2 papers, 2015 to 2023). "PCDHB14 was revealed to be differentially expressed between normal tissue and tumor tissue of colon." (PMID 37237274, 2023). "Protein level of tumor promoting genes (GPRASP1, APLP1, ALPK3, SPTBN5, PCDHB14, LZTS3, RGL2) were higher in tumor tissues." (PMID 37237274, 2023). "We found that most genes with hazard ratio > 1 (GPRASP1, APLP1, ALPK3, SPTBN5, PCDHB14, LZTS3 and RGL2) have a higher expression in tumor tissues than normal tissues except LINGO1 and LZTS1." (PMID 37237274, 2023). "Here, subtype‐specific events involving either DNA copy number loss or CpG promoter methylation were found to involve TENC1, RARA, PCDHB11, PCDHB14, PCDHGA2 and PCDHGB2 indicative of candidate tumor suppressor genes in this context." (PMID 25468711, 2015).
PCDHB14 also shares sentences with these, for which no sentence is quoted: Hypertension (1 paper); neurological disease (1).